LMNA (lamin A/C)
Diseases named in the same sentence as LMNA in open-access papers (continued):
Sharing a sentence is not in itself a finding about the gene and the disease.
cardiomyopathy (continued). "Together, aberrant PRC activity upon LMNA mutation might play an important role in LMNA-related cardiomyopathies." (PMID 36899919, 2023). "The most common phenotypic manifestations of LMNA mutations are cardiomyopathy and myopathy." (PMID 37303410, 2023). "LMNA gene mutations typically present in an autosomal dominant manner and can result in a variety of phenotypes such as lipodystrophy, muscular disease, neuropathy, progeria, and cardiomyopathy." (PMID 37465451, 2023). "As of this writing, over 300 missense, frameshift, nonsense, and splice site mutations throughout the LMNA sequence have been reported in the NIH ClinVar database as pathogenic drivers of cardiomyopathy, muscular dystrophy, lipodystrophy, neuropathy, and other rarer syndromes." (PMID 37619289, 2023). "We, therefore, suspect that the changes in α-tubulin acetylation might explain the Cx43 phenotype in cardiomyopathy caused by mutations in LMNA." (PMID 36550158, 2022). "Here, we show that lamin A/C plays a central role in 3D chromatin architecture in naïve pluripotent stem cells, which ensures proper cardiovascular cell fate, differentiation and function and pinpoints key molecular determinants at the roots of cardiomyopathies due to LMNA loss-of-function (LOF)." (PMID 36333314, 2022). "The indication for primary prevention of sudden cardiac death in patients with HFimpEF is ambiguous, but ICD implantation should be considered in patients with an identified genetic cause of cardiomyopathy at high risk of ventricular arrhythmias (e.g., LMNA, SCN5A, FLNC)." (PMID 36103841, 2022). "Another example is LMNA, in which only specific missense mutations cause lipodystrophy and other variants cause distinct phenotypes including progeria, whereas haploinsufficiency causes cardiomyopathy." (PMID 35235652, 2022). "Here, we demonstrated that the remodeling of cardiac Cx43 in cardiomyopathy caused by mutations in LMNA occurred due to the decreased acetylation of α-tubulin, thus establishing this tubulin post-translational modification as a cause of the cardiac disease phenotype." (PMID 36550158, 2022). "The association between LMNA mutation, lipodystrophy, and cardiac involvement (heart conduction disorders, valvulopathies, and/or cardiomyopathies) has been amply reported, usually manifesting clinically after the third decade, with very high penetrance by the age of 70 years." (PMID 33803191, 2021). "Recently, we showed that elevated high-sensitivity cardiac troponin T (hs-cTnT) serum concentration is the earliest cardiomyopathy indicator in a cohort of DCM-causing lamin A/C gene (LMNA) mutation carriers, preceding arrhythmias, conduction defects and left ventricular systolic dysfunction (LVSD)." (PMID 35054181, 2021). "Mutations in LMNA, encoding lamin A/C, cause different cardiomyopathies including ACM." (PMID 34478111, 2021). "Besides isolated cardiomyopathies, mutations in LMNA cause Hutchinson-Gilford progeria syndrome (MIM, #176,670), a systemic disease leading to premature aging including heart failure." (PMID 34478111, 2021). "Cardiomyopathy caused by mutations in LMNA gene is referred to as cardiolaminopathy (LMNA-CMP)." (PMID 32719615, 2020). "In summary, our study identified failure of DNA repair, dysregulated cell cycle progression and mitochondrial dysfunction/impaired oxidative phosphorylation associated with loss of LMNA, thereby providing mechanistic insights to LMNA cardiomyopathy and heart failure." (PMID 32313136, 2020). "In particular, the heterozygous compound R190Q/R249Q LMNA mutation associated in the patient with severe cardiomyopathy that leads to heart transplantation and severe skeletal muscle wasting, might disrupt Samp1 anchorage by affecting two lamin A/C domains." (PMID 30326651, 2018).
cardiomyopathy (continued). "Among rare diseases caused by mutations in LMNA gene, Emery-Dreifuss Muscular Dystrophy type 2 and Limb-Girdle muscular Dystrophy 1B are characterized by muscle weakness and wasting, joint contractures, cardiomyopathy with conduction system disorders." (PMID 29693488, 2018). "Lamin A/C gene is among the most common cardiomyopathy-causing gene." (PMID 30319452, 2018). "Atomic force microscopy (AFM) cell loading/unloading curves were used to provide comprehensive insights into biomechanical behavior of cardiomyocytes carrying the lamin A/C (LMNA) D192G mutation known to cause defective nuclear wall, myopathy and severe cardiomyopathy." (PMID 26323789, 2015). "The penetrance of the LMNA mutations causing cardiomyopathy is nearly complete." (PMID 21689390, 2011). "Mutations in the lamin A/C gene may cause cardiomyopathy by weakening nuclei, which increase the fragility of nuclei and could be particularly harmful to muscle cells." (PMID 21151901, 2010). "Moreover, even if genetic testing is not routinely applied in AF patients, recent data highlighted that early-onset arrhythmias or a strong family history of AF may be related to pathogenic variants of genes linked to cardiomyopathies, including LMNA." (PMID 35453731, 2022). "It will thus be exciting to study the trafficking of other channels in cardiomyopathy caused by mutations in LMNA, which may help to identify novel therapeutic targets for cardiac disorders that arise from the deficient delivery of ion channels to the plasma membrane." (PMID 36550158, 2022). "Therefore, to determine whether this pathway is involved in LMNA-cardiomyopathy, we investigated the response of LMNA-mutated cardiomyocytes to β-adrenergic stimulation by exposure to isoproterenol (10−9–10−6 M)." (PMID 34360639, 2021). "Cardiomyopathies induced by mutations in LMNA have a very aggressive and fast clinical course that could culminate with sudden cardiac death from malignant ventricular arrhythmias and end-stage heart failure occurring at earlier ages compared to other familial cardiomyopathies." (PMID 30319452, 2018). "The findings are also in agreement with our previous data on the activation of the DDR pathways in other forms of cardiomyopathy, including in mouse models and humans with lamin A/C (LMNA) cardiomyopathy." (PMID 40608429, 2025). "Compared to cardiomyopathies caused by variants in DSP, PKP2, FLNC, and LMNA genes, TTN-CMP and sarcomeric gene-related cardiomyopathies tend to exhibit a similar burden of HF events but a generally lower arrhythmogenic profile." (PMID 41329234, 2025). "Highlighting the robustness of this framework, all ClinGen genes with definitive evidence for Mendelian cardiomyopathy, except LMNA, were prioritized at their respective loci." (PMID 39572783, 2024). "There is an increased prevalence of rare variants (BAG3, LMNA, MYH7, TCAP, TNNT2, and TTN), particularly TTNtv, in adult and pediatric cancer patients with cancer therapy-induced cardiomyopathy." (PMID 39070560, 2024). "Notable genes such as titin (TTN), Bcl2-associated athanogene 3 (BAG3), and lamin A/C (LMNA) are implicated in PPCM, revealing a complex genetic landscape similar to other cardiomyopathies." (PMID 39118717, 2024). "Genetic profiling reveals a complex landscape with key genes like titin (TTN), Bcl2-associated athanogene 3 (BAG3), and lamin A/C (LMNA) implicated in PPCM, suggesting genetic predispositions and shared pathways with other cardiomyopathies." (PMID 39118717, 2024). "Since the key pathogenetic mechanism in this cardiomyopathy seems to be the electrical disturbance in the atria, we analyzed the possible effect of LMNA Q517X expression in HL-1 cardiomyocytes." (PMID 35846372, 2022). "The clinical history of the index family carrying LMNA Q517X mutant, however, puts the permanent atrial fibrillation and conduction defects showed at the onset of the cardiomyopathy as key events for the following heart failure." (PMID 35846372, 2022).
cardiomyopathy (continued). "The majority of LMNA mutations cause the autosomal dominant Emery–Dreifuss muscular dystrophy or EDMD, characterized by progressive muscle wasting, contractures, and cardiomyopathy." (PMID 33396724, 2020). "In this study, we used whole transcriptome DE analysis to investigate the genes and pathways related to LMNA-related cardiomyopathy." (PMID 32698886, 2020). "Mutations in LMNA, EMD and BANF1 are genetically linked to many tissue-specific disorders including Emery-Dreifuss muscular dystrophy and cardiomyopathy (LMNA, EMD), lipodystrophy, insulin resistance and type 2 diabetes (LMNA) and progeria (LMNA, BANF1)." (PMID 31024910, 2019). "In particular, two specific mutations in LMNA gene encoding a nuclear lamina protein were identified as a genetic cause of the HHS type IV characterized by tachyarrhythmia, cardiomyopathy, and brachydactyly." (PMID 29963074, 2018). "Concurrence of both cardiomyopathy and/or conduction defects and FPLD2 due to mutations in LMNA is very rare, but some cases have been reported." (PMID 27504462, 2016). "Emery–Dreifuss muscular dystrophy (EDMD) is a rare inherited myopathy characterized by early-onset contractures of major tendons, progressive skeletal muscle wasting, and cardiomyopathy, most often caused by mutations in the nuclear envelope proteins emerin (EMD) or lamin A/C (LMNA)." (PMID 40558510, 2025). "LMNA cardiomyopathy is caused by mutations in the LMNA, encoding the nuclear proteins lamin A/C." (PMID 39465141, 2024). "ACM-causing mutations have also been identified in genes outside the desmosome, including phospholamban (PLN), filamin C (FLNC), desmin (DES), titin (TTN), and lamin A/C (LMNA), which are linked with other cardiomyopathies, including DCM and neuromuscular cardiomyopathies." (PMID 38610600, 2024). "Here, we summarize the current knowledge on the role of lamin A/C in diseases of the heart muscle and specifically focus on how changes in lamin-A/C-dependent chromatin architecture could be involved in the pathogenesis of cardiomyopathies." (PMID 36899919, 2023). "Pathogenesis of LMNA-related cardiomyopathy remains unclear, but lamin A/C haploinsufficiency may have negative effects on the heart." (PMID 36968203, 2023). "We uncover divergent functions of lamin A/C in naïve pluripotent stem cells and cardiomyocytes, which have distinct contributions to the transcriptional alterations of patients with LMNA-associated cardiomyopathy." (PMID 36333314, 2022). "In fact, this has already been demonstrated for the cardiomyopathy-related gene LMNA and MYBPC3." (PMID 34769381, 2021). "Mutations in the LMNA gene, encoding lamin A and lamin C, cause a wide range of diseases: Emery-Dreifuss muscular dystrophy (EDMD) types 2 and 3, limb girdle muscular dystrophy (LGMD) type 1B, cardiomyopathy, lipodystrophies, peripheral neuropathies, and progeria syndromes." (PMID 32848821, 2020). "In addition, cardiomyopathy, muscular dystrophy, bone and joint abnormalities, as well as lipodystrophy were observed in LMNA-KO rabbits." (PMID 30705772, 2019). "In other words, LMNA mutations may cause DCM, or cardiomyopathy with decreased systolic function, combined with LV dilatation that is too mild to fulfil the criteria of DCM." (PMID 21689390, 2011). "A similar event occurred in myocardial cells in a specific LMNA deletion mice model, which damaged the LINC complex structure caused by knockout or knockdown of SUN1 (a LINC complex protein gene) and in turn, prevented cardiomyopathy progression and extended the lifespan." (PMID 37784143, 2023).
cardiomyopathy (continued). "In addition, inhibitors of this signaling pathway were found to prevent the development of cardiomyopathies associated with a mutation in the LMNA gene, but did not affect the development of muscular dystrophy." (PMID 34722546, 2021). "In addition, cardiomyopathy was found in all death LMNA-KO rabbits." (PMID 30705772, 2019). "However, among MVP patients with mild MR, we also highlight a global, multi-segment pattern of interstitial fibrosis which may underline a diffuse myopathic process initially proposed in genetic studies reporting mutations in cardiomyopathy genes (FLNC, LMNA, ALPK3A)." (PMID 39477155, 2024). "Interestingly, DES, LMNA, TMEM43, and TTN have been associated with either cardiomyopathies or SMD." (PMID 32848821, 2020). "In lamin A/C (LMNA) cardiomyopathy, one of the most arrhythmogenic forms of DCM and thereby comparable to RBM20 cardiomyopathy, end-stage heart failure, rates of MVAs, and mortality are increased in men." (PMID 32789749, 2020). "Although LMNA variants were not independently associated with LVRR in this study probably due to sample size restriction or the presence of confounding factors, our finding that no patients with LMNA variants exhibited LVRR might reflect the natural history of cardiomyopathy with LMNA mutation." (PMID 29386531, 2018). "Furthermore, mutations in LMNA resulting in FPLD2 do not commonly result in cardiomyopathy." (PMID 27504462, 2016). "This pattern was commonly linked to desmosomal (DSP) and non-desmosomal (FLNC, LMNA) genes with both NDLVC and DCM and less often associated with ARVC, HCM, or other cardiomyopathies." (PMID 40238040, 2025). "LMS with non-TTN genetic cardiomyopathies, consisting of mutations in PLN and LMNA genes, exhibited elevated post pause potentiation and efficient contractile force at low pacing frequency." (PMID 40799359, 2025). "Nowadays, findings showed that arrhythmias may be the earliest manifestation in some subtypes of genetic cardiomyopathy, specifically in LMNA- and SCN5A-mediated cardiomyopathies." (PMID 39070560, 2024). "The proband A2 carrying a novel LMNA mutation presents both LGMD phenotype (which can be caused either by LMNA or CAPN3 mutation) and cardiomyopathy (not characteristic for LGMDR1)." (PMID 34720847, 2021). "A very low abundance of lamin A/C has been observed in embryonic cells, and LMNA knockout mice show little or no pathology during development, although postnatal mice develop cardiomyopathy or muscular dystrophy." (PMID 32226788, 2020). "In addition, rapamycin or its analog, temsirolimus, ameliorated cardiomyopathy and improved skeletal and cardiac muscle function in mouse models of LMNA (lamin A/C gene) cardiomyopathy that recapitulate Emery-Dreifuss muscular dystrophy (EDMD)." (PMID 30949479, 2019). "Although LMNA mutations are associated with both cardiomyopathy and FPLD, most patients with FPLD do not develop cardiomyopathy." (PMID 27504462, 2016). "Two recent studies demonstrated that Lmna H222P/H222P as well as Lmna−/− and Lmna+/− embryonic hearts exhibit noncompaction, suggesting these mouse models as important tools to study the developmental origin and the mechanisms behind LMNA-mediated noncompaction cardiomyopathy." (PMID 36899919, 2023).
dilated cardiomyopathy (119 papers, 2010 to 2026). Cardiomyopathy which is characterized by dilation and contractile dysfunction of the left and right ventricles. "Dilated cardiomyopathy caused by variants in the LMNA gene leads to malignant arrhythmogenic events, faster phenotype progression and high risk of sudden cardiac death." (PMID 41580472, 2026). "Our study provides new insights into the molecular mechanisms that determine dilated cardiomyopathy due to pathogenic variants in the LMNA gene, and identified several target pairs that are of potential interest for further studies." (PMID 41580472, 2026). "The LMNA N195K variant is associated with dilated cardiomyopathy, and LmnaN195K/N195K mice develop heart failure and die within 12 weeks of age9." (PMID 41073815, 2025). "Several disease-causing genes have been identified in these contexts, including LMNA (lamin A/C)—typically associated with dilated cardiomyopathy (DCM)—and DES (desmin), more commonly linked to restrictive, arrhythmogenic or mixed phenotypes." (PMID 41464675, 2025). "A novel LMNA p.(Glu105Leu) variant was identified in five families with dilated cardiomyopathy (DCM), revealed as a local founder variant originating approximately 650 years ago." (PMID 40610603, 2025). "An example of an autosomal dominant disease is dilated cardiomyopathy caused by P/LP variants in LMNA.." (PMID 40441529, 2025). "Rare diseases (monogenic), such as hypertrophic cardiomyopathy (e.g., MYBPC3, MYH7 mutations), dilated cardiomyopathy (LMNA, RBM20), or inherited arrhythmias (KCNQ1, RYR2), are often caused by single, well-characterized mutations." (PMID 40465697, 2025). "Later testing showed that the dilated cardiomyopathy was due to an incredibly rare lamin A/C (LMNA) gene mutation, R349L." (PMID 39239135, 2024). "Mutations in the LMNA gene (encoding lamin A/C proteins) cause several human cardiac diseases, including dilated cardiomyopathies (LMNA-DCM)." (PMID 37446344, 2023). "Herein we described a dilated cardiomyopathy family carrying novel variant c.467G > C(p.Arg156Pro) of LMNA as heterozygous pathogenic variant identified by whole-exome sequencing." (PMID 37784143, 2023). "LMNA is one of the most frequently mutated genes associated with dilated cardiomyopathy (DCM), one of the leading causes of severe heart failure and heart transplantation." (PMID 37058558, 2023). "The aim of this study was to understand the clinical and pathogenic characteristics of the LMNA splice-site mutation phenotype in patients with LMNA-related dilated cardiomyopathy (DCM) and sudden cardiac death (SCD)." (PMID 38259623, 2023). "Mutations in the lamin A/C gene (LMNA) cause dilated cardiomyopathy associated with increased activity of ERK1/2 in the heart." (PMID 36550158, 2022). "Mutations in the Lamin A/C(LMNA) gene are commonly associated with cardiac manifestations, such as dilated cardiomyopathy (DCM) and conduction system disease." (PMID 35449878, 2022). "Previous studies in models of dilated cardiomyopathy caused by LMNA gene mutations have shown sarcomeric organization defects associated with abnormal activation of the Cofilin 1, ERK1/2, and p38α pathways in the heart." (PMID 33624748, 2022). "Dominant mutations in LMNA, which encodes nuclear lamin A/C, can cause dilated cardiomyopathy with conduction system disease." (PMID 36550158, 2022). "Most LMNA mutations affect the striated muscles; about 165 LMNA mutations have been associated with dilated cardiomyopathy (DCM)." (PMID 36082133, 2022). "Among the most common genes implicated in dilated cardiomyopathy, it has been estimated that mutations in LMNA gene accounts for about a 10th of familial dilated cardiomyopathy, thus representing one of the major causative genes." (PMID 36274847, 2022).